IDO2 (indoleamine 2,3-dioxygenase 2)
Diseases named in the same sentence as IDO2 in open-access papers (continued):
Sharing a sentence is not in itself a finding about the gene and the disease.
IDO2 also shares sentences with these, for which no sentence is quoted: liver fibrosis (3 papers); renal carcinoma (3); sarcoma (3); brain cancer (2); brain tumor (2); skin melanoma (2); abscess (1); basal cell skin carcinomas (1); cerebral malaria (1); clear cell renal carcinoma (1); colitis (1); dementia (1); diffuse large B-cell lymphoma (1); encephalomyelitis (1); endometriosis (1); glioblastoma (1); Granuloma (1); Hashimoto’s disease (1); Hyperkeratosis (1); immune disorders (1); injury (1); malaria (1); meningioma (1); mesothelioma (1); migraine (1); mood disorder (1); neuroblastoma (1); neurodegenerative disease (1); paraganglioma (1); pheochromocytoma (1).
A further 6 diseases each share a sentence with IDO2 in 1 paper.